SNED1 (sushi, nidogen and EGF like domains 1)
Synonyms: IRE-BP1; FLJ00133; SST3; Snep
Tractability: Antibody: UniProt places it where antibodies can reach, with high confidence; its Gene Ontology location is reachable by antibodies, with high confidence; UniProt predicts a signal peptide or a membrane-spanning region.
Gene: Protein-coding gene on chromosome 2 (240,998,612 to 241,095,569, forward strand). Ensembl gene ENSG00000162804.
Subcellular location: Secreted, extracellular space, extracellular matrix
Gene Ontology:
Molecular function: Notch binding; calcium ion binding
Biological process: cell adhesion mediated by integrin; cell-matrix adhesion
Cellular component: extracellular matrix
Genetic constraint (gnomAD): Loss-of-function variants: 68 observed, 124.92 expected, observed/expected ratio (o/e) 0.54, 90% interval 0.45 to 0.67. The upper end of that interval is the gene's LOEUF score, 0.67, which puts it in group 2 of 6, group 1 being the genes least tolerant of losing a copy. Missense variants: 1,541 observed, 1,785.9 expected, observed/expected ratio (o/e) 0.86, 90% interval 0.83 to 0.9. Synonymous variants: 740 observed, 731.24 expected, observed/expected ratio (o/e) 1.01, 90% interval 0.95 to 1.08.
Homologues: Orthologues: chimpanzee SNED1 (97% identical), macaque SNED1 (96% identical), pig SNED1 (85% identical), rat Sned1 (84% identical), mouse Sned1 (84% identical), guinea pig SNED1 (83% identical), dog SNED1 (82% identical), tropical clawed frog sned1 (54% identical), zebrafish sned1 (50% identical). Paralogues in human: NOTCH1 (28% identical), NOTCH2 (27% identical), NOTCH3 (27% identical), NOTCH2NLR (2% identical), NOTCH2NLC (2% identical), NOTCH2NLB (2% identical), NOTCH2NLA (2% identical).
Diseases named in the same sentence as SNED1 in open-access papers:
SNED1 is named in the same sentence as 32 diseases in open-access papers, as found by Europe PMC text mining. Sharing a sentence is not in itself a finding about the gene and the disease. The quoted sentences say what the papers report.
breast carcinoma (9 papers, 2013 to 2025). "Here, we report that SNED1 mediates the adhesion of breast cancer cells and neural crest cells, two cell types of relevance to the in vivo functions of SNED1." (PMID 39713860, 2025). "Our study is thus the first to report the identification of SNED1 receptors and constitutes an important step toward the identification of the biochemical signaling events leading to SNED1-dependent breast cancer metastasis and craniofacial development." (PMID 39713860, 2025). "The murine gene Sned1 was cloned two decades ago; however, it took 10 years to identify its first function as a promoter of breast cancer metastasis." (PMID 39713860, 2025). "High levels of SNED1 expression promote invasiveness during breast cancer metastasis, suggesting a possible mechanical role in tissue remodeling." (PMID 30409788, 2019). "We showed that LTBP3 and SNED1, identified by proteomics in our study as differentially expressed between poorly and highly metastatic mammary tumors, correlate at the transcript level with clinical outcome in a cohort of ER−/PR− breast cancer patient." (PMID 24618895, 2014). "We have recently identified a novel ECM protein, SNED1, and have found that it is required for neural crest cell migration and craniofacial morphogenesis during development and in breast cancer, where it is necessary for the metastatic dissemination of tumor cells." (PMID 39713860, 2025). "Here, we report that SNED1 mediates breast cancer and neural crest cell adhesion via its RGD motif." (PMID 39713860, 2025). "SNED1, a Sushi, Nidogen, and EGF-like Domain 1 extracellular matrix protein, is associated with progression and metastasis of mammary carcinomas and with poor outcomes in ER−/PR− breast cancer." (PMID 32586373, 2020). "In addition, we show that Ltbp3 and Sned1 mRNAs are up-regulated during malignant progression in the autochthonous MMTV-PyMT murine mammary tumor model." (PMID 24618895, 2014). "Other coding SNPs that could include causal variants producing synthetic associations (associations of rare with common SNPs of high penetrance) include SNPs in genes INS-IGF2, ZFYVE26, C16orf46, UNC13A, NRIP1 and CCDC91 for breast cancer and SNPs in SNED1 and PASK for prostate cancer." (PMID 23555315, 2013). "While expression levels for SNED1 and LTBP3 were not significantly correlated across all mammary cancer sub-types, they were significantly correlated (p values of 0.0079 and 0.034, respectively) with poor prognosis for estrogen-receptor-negative and progesterone-receptor-negative (ER−/PR−) patients." (PMID 24618895, 2014).
breast tumors (1 paper, 2014). "As demonstrated for SNED1 and LTBP3, other proteins that are part of the proteomic signatures of highly and poorly metastatic breast tumors described here, may prove to correlate with patient outcomes and may prove useful as novel prognostic and diagnostic biomarkers." (PMID 24618895, 2014).
keloid (1 paper, 2022). An irregularly shaped, elevated mark on the skin caused by deposits of excessive amounts of collagen during wound healing. "Using qPCR, three genes (SNED1, NIPAL3, and VTN) among 14 candidate genes were shown to be significantly changed by HOXA11-AS-knockdown keloid fibroblasts compared with normal keloid fibroblasts." (PMID 35432479, 2022). "Three genes, including SNED1, NIPAL3, and VTN, were validated by real-time PCR in HOXA11-AS-knockdown keloid fibroblasts." (PMID 35432479, 2022). "We obtained three PCR-validated genes (NIPAL3, SNED1, and VNT) without any detectable proteins by western blotting, even in normal keloid fibroblasts without HOXA11-AS knockdown." (PMID 35432479, 2022). "However, no detectable expression of SNED1, NIPAL3, and VTN was shown in either normal or HOXA11-AS-knockdown keloid fibroblasts using western blotting (data not shown)." (PMID 35432479, 2022).
meningioma (1 paper, 2023). A generally slow growing tumor attached to the dura mater. "Investigation of antigen distribution across all WHO grades yielded six common meningioma-associated antigens (A4GALT, FBN2, SNED1, MPP6, PCED1B, and ANGEL2)." (PMID 37368072, 2023).
Obesity (1 paper, 2020). Accumulation of substantial excess body fat. "SNED1 in humans is known as insulin-responsive sequence DNA-binding protein 1 (IRE-BP1); it is a transcription factor involved in the determination of BMI and the activation of insulin-responsive genes and obesity." (PMID 32544202, 2020).
tumor (7 papers, 2014 to 2025). "Both gene lists contained genes associated with tumor progression and metastasis, such as CDK6, SNED1, and MTDH." (PMID 37234983, 2023). "In this study, we report for the first time a functional role for SNED1 in tumor progression and metastasis and we now wish to understand the molecular mechanisms by which SNED1 contributes to tumor progression." (PMID 24618895, 2014). "ACAT2 and SPHK1 were related to lipid metabolism and some tumor-promoting pathways, SNED1 might be related to cell matrix adhesion." (PMID 37202800, 2023). "LTBP3 and SNED1 likely act early in the metastatic cascade by promoting tumor invasiveness." (PMID 24618895, 2014). "In contrast, knockdown of LTBP3 or SNED1 in LM2 cells did not affect lung colonization, consistent with our finding that these proteins influence tumor cell invasion at the primary site." (PMID 24618895, 2014).
cancer (1 paper, 2023). A tumor composed of atypical neoplastic, often pleomorphic cells that invade other tissues. "We performed immunohistochemical analysis of ACAT2, SPHK1, SNED1, KPNA2, BZW2 and KIF15 in cancer and normal tissues and statistically analyzed the staining intensity." (PMID 37202800, 2023).
infection (1 paper, 2019). The state of being infected such as from the introduction of a foreign agent such as serum, vaccine, antigenic substance or organism. "Following infection at 10 dpi, six of the DEGs were immune genes (GAL1, GAL2, GAL7, ABCB1, LEPR and SNED1) and two were involved in NOD-like receptor signaling pathway (K60 and HSP90B1), all were upregulated in expression in line 63 birds." (PMID 31578366, 2019).
SNED1 also shares sentences with these, for which no sentence is quoted: gastric cancer (2 papers); amyotrophic lateral sclerosis (1); cervical cancer (1); colorectal cancer (1); diabetes (1); endometrial cancer (1); endothelial dysfunction (1); glioma (1); heart failure (1); hyperglycaemia (1); ischemic cardiomyopathy (1); ischemic heart disease (1); liver cancer (1); lung carcinoma (1); myocardial infarct (1); ovarian carcinoma (1); pancreatic cancer (1); prostate adenocarcinoma (1); prostate carcinoma (1); renal carcinoma (1); ST Elevation Myocardial Infarction (1); stomach cancer (1); thyroid cancer (1); triple-negative breast carcinoma (1).